MCOLN3 (mucolipin TRP cation channel 3)
Description:
Nonselective cation channel probably playing a role in the regulation of membrane trafficking events. Acts as a Ca(2+)-permeable cation channel with inwardly rectifying activity. Mediates release of Ca(2+) from endosomes to the cytoplasm, contributes to endosomal acidification and is involved in the regulation of membrane trafficking and fusion in the endosomal pathway. Also permeable to Mg(2+), Na(+) and K(+) (By similarity). Does not seem to act as mechanosensory transduction channel in inner ear sensory hair cells. Proposed to play a critical role at the cochlear stereocilia ankle-link region during hair-bundle growth (By similarity). Involved in the regulation of autophagy. Through association with GABARAPL2 may be involved in autophagosome formation possibly providing Ca(2+) for the fusion process (By similarity). Through a possible and probably tissue-specific heteromerization with MCOLN1 may be at least in part involved in many lysosome-dependent cellular events. Possible heteromeric ion channel assemblies with TRPV5 show pharmacological similarity with TRPML3.
Synonyms: TRPML3; FLJ11006; TRP-ML3
Tractability: Small molecule: it belongs to a druggable protein family. Antibody: UniProt places it where antibodies can reach, with high confidence; its Gene Ontology location is reachable by antibodies, with high confidence; UniProt predicts a signal peptide or a membrane-spanning region. PROTAC: ubiquitination databases record sites on it; a small molecule that binds it is known.
Target class: Voltage-gated ion channel; Ion channel; Transient receptor potential channel
Chemical probes: ML122, ML268, ML269, SF-21
Gene: Protein-coding gene on chromosome 1 (85,018,082 to 85,048,679, reverse strand). Ensembl gene ENSG00000055732.
Subcellular location: Cell membrane; Early endosome membrane; Late endosome membrane; Lysosome membrane; Cytoplasmic vesicle, autophagosome membrane
Pathways (Reactome):
Transport of small molecules: TRP channels
Gene Ontology:
Molecular function: calcium channel activity; monoatomic anion channel activity; NAADP-sensitive calcium-release channel activity; potassium channel activity; sodium channel activity; monoatomic cation channel activity
Biological process: calcium ion transmembrane transport; calcium-mediated signaling; monoatomic anion transmembrane transport; potassium ion transmembrane transport; sodium ion transmembrane transport
Cellular component: early endosome membrane; late endosome membrane; lysosomal membrane; plasma membrane; autophagosome membrane; cytoplasm
Genetic constraint (gnomAD): Loss-of-function variants: 58 observed, 62.41 expected, observed/expected ratio (o/e) 0.93, 90% interval 0.75 to 1.16. The upper end of that interval is the gene's LOEUF score, 1.16, which puts it in group 5 of 6, group 1 being the genes least tolerant of losing a copy. Missense variants: 522 observed, 638.95 expected, observed/expected ratio (o/e) 0.82, 90% interval 0.76 to 0.88. Synonymous variants: 173 observed, 215.17 expected, observed/expected ratio (o/e) 0.8, 90% interval 0.71 to 0.91.
Homologues: Orthologues: chimpanzee MCOLN3 (99% identical), macaque MCOLN3 (98% identical), guinea pig MCOLN3 (94% identical), dog MCOLN3 (94% identical), rat Mcoln3 (92% identical), mouse Mcoln3 (91% identical), rabbit MCOLN3 (91% identical), pig MCOLN3 (87% identical), tropical clawed frog mcoln3 (74% identical), zebrafish MCOLN3 (57% identical), zebrafish mcoln3a (54% identical), Drosophila melanogaster CG42638 (41% identical), and 2 more. Paralogues in human: MCOLN2 (56% identical), MCOLN1 (55% identical).
Diseases named in the same sentence as MCOLN3 in open-access papers:
MCOLN3 is named in the same sentence as 33 diseases in open-access papers, as found by Europe PMC text mining. Sharing a sentence is not in itself a finding about the gene and the disease. The quoted sentences say what the papers report.
atherosclerosis (1 paper, 2022). A disease characterized by the build-up of fatty material and calcium deposition in the arterial wall resulting in partial or complete occlusion of the arterial lumen. "Thus, an association has been established between several stretch-specific miR-1183 targets and cardiac remodeling, such as: KCNA3 with diabetic cardiomyopathy, MED23 with CHD, SAMSN1 with atherosclerosis, CCND1 with myocardial ischemia-reperfusion injury, and MCOLN3 with atrial fibrillation." (PMID 35805966, 2022).
glioma (1 paper, 2022). A benign or malignant brain and spinal cord tumor that arises from glial cells (astrocytes, oligodendrocytes, ependymal cells). "Higher levels of TRPC4, TRPC6, MCOLN1, MCOLN2, and MCOLN3 were significantly associated with shorter OS times in glioma." (PMID 35625048, 2022). "In our present study, the results showed that the expression of TRPC1 and TRPC3 was significantly increased in glioma with IDH mutation status and 1p/19q codeletion status, while the expression of TRPC6, MCOLN1, MCOLN2, and MCOLN3 was significantly decreased." (PMID 35625048, 2022). "The gene expression levels of TRPC1, TRPC3, and TRPC5 were significantly higher in low-grade glioma (LGG), while the levels of TRPC4, TRPC6, TRPM7, MCOLN1, MCOLN2, and MCOLN3 were significantly higher in high-grade glioma (HGG)." (PMID 35625048, 2022). "Among the eight final identified hub genes, higher expression levels of TRPC1, TRPC3, and TRPC5 were significantly associated with longer OS time in glioma, while higher expression levels of TRPC4, TRPC6, MCOLN1, MCOLN2, MCOLN3 were significantly associated with shorter OS time." (PMID 35625048, 2022).
Hypertension (1 paper, 2026). The presence of chronic increased pressure in the systemic arterial system. "The subject harboring the MCOLN3 N411_V412delinsI mutation presented with more pronounced clinical features, including severe hypertension and hypokalemia, compared to those with the MCOLN3 Y391D missense mutation." (PMID 41601940, 2026).
keloid (1 paper, 2025). An irregularly shaped, elevated mark on the skin caused by deposits of excessive amounts of collagen during wound healing. "Additionally, 14 genes such as GRIN2D, HTR7, and CCKAR were found to be upregulated in the calcium signaling pathway, while 43 genes, including ATP2A1, ADCY8, and MCOLN3, were significantly downregulated, suggesting that calcium signaling plays a critical role in the pathology of keloids." (PMID 41562114, 2025).
prion disease (1 paper, 2023). A transmissible disease that is caused by a protein that is able to induce abnormal folding of normal cellular proteins, leading to characteristic spongiform brain changes, which are associated with neuronal loss without an inflammatory response. "Though increased overall during prion disease, the genes Clec7a, Itgam, and Mcoln3 were significantly decreased in CD11c-/- relative to C57BL/6 mice at the clinical stage of prion disease." (PMID 37910561, 2023).
cancer (6 papers, 2019 to 2023). A tumor composed of atypical neoplastic, often pleomorphic cells that invade other tissues. "The high-risk group expressing MCOLN3 is enriched with multiple oncological signatures and pathways involved in cancer aggressiveness and associated with significantly lower levels of CD4+ T cell infiltration." (PMID 32411610, 2020). "Moreover, the data analysis, using The Cancer Genome Atlas (TCGA) database, showed that MCOLN3 is downregulated in several cancer types, and it is associated with a relatively better survival in kidney renal clear cell." (PMID 32411610, 2020). "The roles of MCOLN3 and SLC25A45 in cancer are worthy of further investigation." (PMID 31612115, 2019). "The roles of MCOLN3 and SLC25A45 in cancer development have not yet been elucidated." (PMID 31612115, 2019).
tumor (6 papers, 2014 to 2025). "The three genes (MCOLN1, MCOLN2, and MCOLN3) coding for the mucolipin subfamily of TRP channels were also down-regulated in tumor tissues." (PMID 24466154, 2014). "The downregulated MCOLN3 and SLC25A45 with HR < 1 were considered as tumor suppressors, whereas the upregulated COL17A1, CEP55, KLK10, MET, ITGB6, ANKRD22, and ARNTL2 with HR > 1 were regarded as oncogenes." (PMID 31612115, 2019). "In contrast, MCOLN3 and SLC25A45 were significantly decreased in compare with non-tumor tissues." (PMID 31612115, 2019).
MCOLN3 also shares sentences with these, for which no sentence is quoted: deafness (6 papers); pancreatic cancer (4); emphysema (3); infection (2); melanoma (2); viral infections (2); abetalipoproteinemia (1); Ataxia (1); atrial fibrillation (1); bacterial infection (1); chronic obstructive pulmonary disease (1); diabetic cardiomyopathy (1); hearing loss (1); Hypokalemia (1); infectious disease (1); ischemia (1); lung (1); mucolipidosis type IV (1); myeloma multiple (1); neurodegenerative disease (1); paraganglioma (1); pheochromocytoma (1); retinal degeneration (1); stomach adenocarcinomas (1); thymoma (1); uterine carcinosarcoma (1).